IL6 (interleukin 6)
Diseases named in the same sentence as IL6 in open-access papers (continued):
Sharing a sentence is not in itself a finding about the gene and the disease.
acne (80 papers, 2013 to 2025). An inflammatory process of the sebaceous glands which is characterized by comedones, nodules, papules and/or pustules on the skin. "These host cells had less IL-8 and IL-6 release after exposure to acne-associated C-type strains than to the health-associated K-type strains." (PMID 37478901, 2024). "IL-6 is one of the major acne lesion-associated cytokines and is predominant in the inflammatory lesions of acne vulgaris." (PMID 38792208, 2024). "The activation of the NLRP3 inflammasome promotes the maturation of caspase-1 and triggers the release of the downstream acne-pathogenic cytokines IL-1β and IL-18, which subsequently activates the secondary inflammatory mediators, including IL-6 and IL-832." (PMID 38062074, 2023). "Two studies also found a significant association between IL6 − 572 G/C variants and acne presentation." (PMID 33849530, 2021). "This is consistent with our observation of significantly elevated IL-6 levels (p < 0.01), a cytokine known to promote keratinocyte proliferation and sebocyte differentiation in acne." (PMID 41614864, 2025). "In the present study, IL-6 levels were significantly higher in patients with severe and moderate acne grades." (PMID 40851686, 2025). "Palmitic acid, a major component of sebum, has been shown to increase pro‐inflammatory cytokines IL‐6 and IL‐8 in sebocytes and can contribute to the pathogenesis of acne by promoting clogged pores." (PMID 41312576, 2025). "These genes, validated by significant IL-6 upregulation (p < 0.01), are promising biomarkers for acne severity and potential therapeutic targets." (PMID 41614864, 2025). "The abundance of neutrophils in pustular and cystic lesions likely explains the elevated IL-6 levels in patients with severe acne." (PMID 40851686, 2025). "Their haemolytic activity and ability to induce pro-inflammatory cytokines, such as IL-6 and IL-8, suggest a complex role in acne pathogenesis." (PMID 40668089, 2025). "In acne pathogenesis, the upregulation of Th17-related cytokines such as IL-8, IL-1β, IL-6 and TGF-β is well documented." (PMID 40668089, 2025). "This is likely due to enhanced neutrophil recruitment and Th17-mediated inflammation, where Th17 cells are believed to be the major source of IL-6 in acne lesions." (PMID 40851686, 2025). "In acne treatment, the production of IL-6 is regulated by IL-1β and TNF-α, which further amplifies the inflammatory cascade." (PMID 39942620, 2025). "The findings of our study highlight a strong association between acne severity and elevated levels of inflammatory (Hs-CRP, IL-6) and oxidative stress (MDA) markers, supporting their role in the pathogenesis of the disease." (PMID 40851686, 2025). "Excess lipid accumulation in ASCs and sebocytes stimulates the release of pro-inflammatory cytokines, such as TNF-α and IL-6, aggravating skin inflammation, promoting sebaceous gland activity, and exacerbating acne through mTOR signaling activation." (PMID 40227405, 2025). "Borneol also effectively treats acne because of its anti-inflammatory and analgesic effects, and was found to inhibit acne-mediated production of IL-6, IL-1β, interleukin-8 (IL-8) and TNF-α by inhibiting the NFκB activation pathway." (PMID 41573729, 2025). "As a result, agents that act suppressing the ROS, IL‐1β and IL‐6 productions have been widely used for acne treatment." (PMID 38426932, 2024). "IL-6 is an important inflammatory factor in the development of diseases such as common acne and seborrheic dermatitis." (PMID 39114361, 2024). "Its anti-inflammatory action includes reducing pro-inflammatory cytokines such as TNF-α and IL-6, while its antimicrobial properties help combat acne-related bacterial overgrowth." (PMID 39684852, 2024). "We next investigated the effects of RPE and PPH on the induction of key proinflammatory cytokines during the acne pathogenesis (IL‐1β and IL‐6) in LPS‐stimulated RAW 264.7 cells." (PMID 38426932, 2024).
acne (continued). "Cutibacterium acnes stimulates sebocytes to produce interleukin (IL)-6 and IL-8 and other cytokines, thereby aggravating inflammatory responses in acne progression." (PMID 38062074, 2023). "In acne lesions, C. acnes invasion stimulates sebaceous gland activity, resulting in excessive sebum secretion and the release of IL-6, IL-1β, IL-8, TNF-α8." (PMID 38062074, 2023). "L. rhamnosus significantly improved acne-like symptoms in rats by suppressing the level of inflammatory cytokines such as IL-1β, IL-6, and TNF-α." (PMID 38250060, 2023). "Subsequently, chemokines, including TNF-α, IL-8 and IL-6, were transcribed, which triggers inflammatory cell infiltration in acne skin." (PMID 35211023, 2022). "Pro-inflammatory cytokines, such as IFN-γ, TNF-α, IL-6, and IL-8, are already known to be upregulated in acne lesions." (PMID 35328573, 2022). "TNF-α, IL-6 and IL-1β are inflammatory molecules involved in both acute and chronic inflammatory acne." (PMID 36145700, 2022). "NF-κB increases the expression of pro-inflammatory factors including interleukin 1β (IL-1β), IL-6 and tumor necrosis factor alpha, three of which are essential in acne pathology." (PMID 35211023, 2022). "Further, H. leonuri also reduced the acne in a rat ear acne model by the reduction of serum IL-6 levels." (PMID 35889539, 2022). "In acne inflammation pathogenesis, C. acnes plays an important trigger role through IL-6 and IL-8 secretion by follicular keratinocytes and IL-1β, TNF-α, IL-8 and IL-12 by monocytes." (PMID 36145700, 2022). "Patients suffering from acne vulgaris presented high levels of IL-8 in peripheral blood mononuclear cells and remarkable expression of IL-6 and IL-8 in keratinocytes." (PMID 36145700, 2022). "Inflammatory markers such as IL-1, IL-6, IL-8, MMPs, and TNFα are the most relevant cytokines expressed in acne pathogenesis." (PMID 35910763, 2022). "The results indicate that TAN has therapeutic efficacy for acne, as supported by the results of the histological analyses and biochemical index assays for interleukin (IL)-8, IL-6, IL-β and tumor necrosis factor alpha." (PMID 34177586, 2021). "Activation of the Th17 cell that induced IL-6 secrete IL-17A and IL-17F which main effector cytokines in acne lesions." (PMID 32380665, 2020). "Among cytokines, interleukin (IL)-1β and IL-6 were significantly higher in the PS acne group than in the control group." (PMID 31951642, 2020). "To treat acne vulgaris (AV), we evaluated the inhibition of inflammatory cytokines (IL-6 and IL-8) of QM leaf extract (QML) and its main compound, pedunculagin (PD) in vitro and 5α-reductase inhibitory activity by western blotting." (PMID 32380665, 2020). "The most refractory complication of acne is scar formation, which involves the production of pro-inflammatory cytokines such as IL-1α, IL-1β, IL-6, TNF-α, and TGF-β54." (PMID 32765835, 2020). "Serum IL-6 levels are significantly higher in acne patients than in the normal population, suggesting a vital role for IL-6 in the pathogenesis of acne." (PMID 30120655, 2019). "It seems that 5-LOX activation is followed by production of inflammatory factors such as IL-6 and IL-8 in acne patients." (PMID 34466486, 2019). "Nevertheless both cytokines are robust inducers of IL-6 and IL-8 gene expression and propagate an initial inflammatory response of the pilosebaceous unit in acne." (PMID 25894228, 2015). "A number of proinflammatory cytokines, including interleukin-6 (IL-6), tumor necrosis factor-α (TNF-α), and interleukin-1β (IL-1β), have been implicated in the inflammatory process of acne." (PMID 24078775, 2013). "Serum IL-6 levels were significantly higher in acne patients than that in normal population, suggesting a role for IL-6 in the pathogenesis of acne." (PMID 24078775, 2013).
acne (continued). "Myeloid cells play important roles in acne development by responding to Propionibacterium acnes (P. acnes) and producing proinflammatory factors such as interleukin (IL)−1β, IL-6, IL-8, and tumor necrosis factor α (TNFα), which contribute significantly to acne inflammation." (PMID 41307843, 2025). "The elevated levels of Hs-CRP observed in severe-grade acne in our study may be attributed to the increased number of inflammatory lesions and the concurrent elevation of cytokines such as IL-6 and TNF-α, which stimulate the hepatic production of CRP." (PMID 40851686, 2025). "Some findings suggest that IL-6 in vitro can stimulate SZ95 cell lipid synthesis, indicating that IL-6 may also be involved in the occurrence of diseases like common acne by regulating the biological function of sebaceous gland cells." (PMID 39114361, 2024). "The elevated expression of IL-6 has been found in acne-affected skin." (PMID 38249466, 2023). "Even in acne, 1,8-Cineol-containing leaf extracts suppress the expression of IL-1β and IL-6." (PMID 37570874, 2023). "This review highly recommended further association studies for the candidate genes including IL6, FAS, and IFNG to identify the genetic variants playing unknown roles in the pathogenicity of acne vulgaris and receiving medications." (PMID 37228537, 2023). "Furthermore, the number of IL-6-expressing F4/80+ macrophages was consistently lower in PDTC-treated acne lesions." (PMID 36901873, 2023). "Elevated expression levels of IL-6 and IL-8 in acne lesions also have been reported." (PMID 38193084, 2023). "Thus, cytokines orchestrating the immune response in acne includes Interleukin 1β (IL-1β), Interleukin 6 (IL-6), Interleukin 8 (IL-8), and Tumor Necrosis Factor alpha (TNFα) involved in the inflammatory pathogenesis." (PMID 35910763, 2022). "In addition, while the role of SEMA4B in acne pathogenesis is uncertain, it is known to be involved in immune responses and downregulates the secretion of IL-4 and IL-6 in basophils." (PMID 33849530, 2021). "Interleukin (IL)-1α and IL-6 are predominant in the inflammatory lesions of acne vulgaris." (PMID 32627753, 2020). "IL-6 exacerbates acne by promoting inflammation in the skin." (PMID 32627753, 2020). "The other cytokines related to pathogenesis of acne vulgaris are IL-6, IL-8, IL-10, and IL-12." (PMID 29805787, 2018). "Similarly, T37 had severe acne at age 25, but we found high‐level IL‐6 antibodies only >10 years later." (PMID 27957331, 2016). "In light of these observations and the modulating effect of APS on NF-κB activation other target genes than IL-6 or IL-8 may be affected by APS at the protein level in vivo in acne patients." (PMID 25894228, 2015). "In this context, we suggested that PA may also contribute to acne inflammation via increasing IL-6 secretion." (PMID 24078775, 2013). "The obtained results show a nearly complete ablation in the formation of IL-1α, IL-8 and IL-6, which subsequently prevents the inflammatory cytokines from mediating innate and adaptive immunity and multiple physiological processes, thus preventing the onset of acne-induced skin inflammation." (PMID 36838382, 2023). "Thus, variants in VDR, IL6 and IL8 may affect sebaceous gland function and contribute to acne development or exacerbation." (PMID 33849530, 2021). "Therefore, inhibition of P. acnes-induced IL-6 and IL-1α expression could relieve the symptoms of acne." (PMID 32627753, 2020). "Importantly, evidence from previous publications shows that IL-6 is elevated in patients with acne, suggesting that this inflammatory cytokine also may contribute to the development of acne." (PMID 24078775, 2013). "It downregulates TNF-α, IL-6, PGE2, and COX-2 and is widely incorporated into anti-acne and soothing skin-care formulations." (PMID 41007180, 2025). "Some target genes were likely involved in acne development, including AR, IGF1/IGF1R, mTOR, GATA6, Wnt, IL6, FOXO1, PIK3, MYC." (PMID 40625748, 2025).
acne (continued). "Proinflammatory cytokines such as interleukin-1 (IL-1), IL-6, and tumor necrosis factor (TNF)-α, are known modulators of inflammatory responses in acne." (PMID 40851686, 2025). "The primary objective of this study was to estimate inflammatory markers such as high-sensitive C-reactive protein (Hs-CRP), interleukin-6 (IL-6) and an oxidative stress marker, malondialdehyde (MDA), in acne patients." (PMID 40851686, 2025). "CPT contributes to reducing the levels of inflammatory cytokines IL-1β, IL-6, IL-8, and TNF-α in acne model rats." (PMID 40230697, 2025). "Tanshinone can reduce the levels of IL-8, IL-6, IL-1β, and TNF-α in acne model rats, as profiled by lipidomics, with the mechanism possibly related to sphingolipid and glycerophospholipid metabolism pathways." (PMID 40230697, 2025). "The experimental results confirmed that GA inhibited lipid synthesis in vitro and in vivo, improved the symptoms of acne vulgaris, prevented mast cell infiltration and decreased the level of pro-inflammatory cytokines, including TNF-α, IL-1β and IL-6." (PMID 38792208, 2024). "Based on the PPI network analysis and topology algorithm in Cytoscape software, TNF, GAPDH, IL6, Albumin (ALB), and protein kinase 1 (AKT1) are considered to be the core target proteins for the treatment of acne." (PMID 39029003, 2024). "It was found that baicalin significantly decreased the expression of M1 macrophage-related cytokines such as IL-1β, IL-6, TNF-α and NLRP3 in acne models, and inhibited the M1 polarization of macrophages by inhibiting the nuclear translocation of NF-κB p65." (PMID 38736879, 2024). "PPAR-γ, TNF, IL-1β, IL-6, TLR and NFκB1 were identified as potential core targets of GA in the regulation of acne vulgaris." (PMID 38792208, 2024). "In this study, we observed that keratinocytes secreted IL-6 and MCP-1 during acne induction through a TLR2-calcium-related signaling mechanism distinct from that of macrophages." (PMID 39588538, 2024). "The binding of active androgens to AR can stimulate macrophages to secrete pro-inflammatory factors IL-1, IL-6, and TNF-α, which is consistent with the inflammatory response observed at acne lesion sites." (PMID 38736879, 2024). "In parallel investigations, CBD treatment at 10 μM within an LPS-induced acne-like context exhibited decreased levels of TNF-α, IL-1β, and IL-6." (PMID 38904694, 2024). "In contrast, the sebum of acne patients contains elevated levels of PA, which may also play a role in the pathogenesis of acne by enhancing the secretion of interleukin (IL)-1β in in vitro differentiated monocyte-derived macrophages and the production of IL-6 and IL-8 by human sebocytes." (PMID 37571253, 2023). "Proinflammatory cytokines such as IL-1β, IL-6, IL-8, and TNF-α are responsible for the follicular keratinization and inflammation of acne." (PMID 35947554, 2022). "Sebocytes also promote T cell differentiation into Th17 cells, via IL-6, TGF-β and IL-1β production that are released during acne development." (PMID 35910763, 2022). "It is worth noting that, cytokines, i.e., IL-1β and IL-6 i TGF-β, were also found in acne lesions, and they play a significant role in the activation of Th17." (PMID 35329904, 2022). "Nitrate oxide can be an alternative treatment for acne in humans by reducing IL-1β, IL-8, TNF-α, and IL-6 induced by monocytes and IL-8 and IL-6 induced by keratinocytes via innate immunity." (PMID 32765835, 2020). "The present study is the first to evaluate the serum levels of IL-1α, IL-1β, IL-6, IL-8, IL-12β, IL-15, TNF-α, and granulocyte-macrophage colony-stimulating factor in acne subjects compared with the levels in healthy controls." (PMID 31951642, 2020). "In clinical acne samples, P. acnes triggers activation of TLR-2 which modulates production of inflammatory cytokines, including TNF-α, IL-1β, IL-6, and IL-87,30." (PMID 29507345, 2018).
acne (continued). "The proinflammatory cytokines IL-1β, IL-6, TNF-α and the chemokine IL-8 were all expressed at a higher level in acne lesions in the Finnish cohort." (PMID 25153527, 2014). "There were differences in Hs-CRP, IL-6 and MDA levels based on the severity of acne vulgaris." (PMID 40851686, 2025). "Indeed, the inflammatory milieu in sebocytes, as evidenced by increased levels of cytokines, including IL-6, IL-8, and IL-1β, and the lipid metabolism enzyme COX-2, is reportedly elevated in acne." (PMID 39944487, 2025). "The core targets of the treatment of acne were TNF, GADPH, IL-6 and so on." (PMID 39029003, 2024). "A total of 37 potential targets were predicted by network pharmacology, among which TNF, IL-1B, IL-6, ESR1, PPARG, NFκB1, STAT3, and TLR4 may be the key targets of GA in the treatment of acne." (PMID 38792208, 2024). "IL-6, IL-8, IL-1β, and TNF-α are the most well-studied cytokines in acne research." (PMID 38193084, 2023). "Besides, isoglycyrrhizin inhibits inflammatory cytokines like IL-6, IL-8, TNF-α and IL-1β in NF-κB, p38 and ERK pathways in multi cells, all of which have been reported to be closely related to acne." (PMID 35211023, 2022). "As shown in the cytokine levels in serum of IL-6, IL-8, TNF-α and IL-1β, the CPT could inhibit the release of these cytokines, thus improving inflammation in acne rats." (PMID 34539397, 2021). "Moreover, PA treatment was shown to increase the secretion of IL6 and IL8 in SZ95 sebocytes, cytokines that contribute to inflammation in acne lesions." (PMID 34025636, 2021). "Moreover, nuclear factor (NF)-κB, activator protein (AP)-1, pro-inflammatory cytokines (TNF-α, IL-1β, IL-6, and IL-8), and metalloproteinases (MMP) are activated via upregulation of TLR-2 in facial acne lesions of patients." (PMID 29507345, 2018). "Our data further suggest that the beneficial effect of APS in acne patients involves attenuation of NF-κB signaling but not reduction of IL-6 or IL-8 secretion." (PMID 25894228, 2015). "Similarly, TLR2 and TLR4 as well as IL-8, IL-6, and TNF-α, were induced in acne lesions in the German group." (PMID 25153527, 2014). "Besides IL-6, we also found that TNF-α and IL-1β were increased following PA treatment, which are also critically important in acne inflammation." (PMID 24078775, 2013). "As limited work has been done considering all the parameters (Hs-CRP, IL-6 and MDA) simultaneously, in our tertiary care center, the present study focused on evaluating the serum levels of these markers in patients with acne and assessing whether a correlation exists with disease severity." (PMID 40851686, 2025). "HVE (5–250 μg/mL) also demonstrated inhibitory activity against the NF-κB-driven transcription and the correlated IL-6 and IL-8 release in keratinocytes challenged with C. acnes infection or TNF-α, suggesting a possible role against the topical inflammation occurring in acne." (PMID 35740016, 2022). "Moreover, the prominent induction of genes, such as PTGS2, CXCL8, IL6, IL1B, matrix metalloproteinase 1 (MMP1) and NLRP3, even raised the possibility that EGF and PA may be involved in the pathogenesis of acne." (PMID 34025636, 2021). "The finding shows that APS neither reduces IL-6 and IL-8 protein expression nor affects PGE2 secretion in SZ95 sebocytes suggests another mechanism of action of this agent in patients with acne vulgaris." (PMID 25894228, 2015). "The expression of cytokines IL-6, IL-12p40, INF-γ and TGF-β have not been studied earlier in acne lesions as also noticed by Thiboutot and co-workers, nor cytokines IL-17A, IL-17F, IL-23p19, IL-22 and chemokines CCL20 and CSF2." (PMID 25153527, 2014).